CASZ1 (castor zinc finger 1)
Diseases named in the same sentence as CASZ1 in open-access papers (continued):
Sharing a sentence is not in itself a finding about the gene and the disease.
atherosclerosis (1 paper, 2025). A disease characterized by the build-up of fatty material and calcium deposition in the arterial wall resulting in partial or complete occlusion of the arterial lumen. "Another limitation of this study is that we used transient KD approaches to address the roles of Casz1 and Zfp961 in the regulation of plasma lipoproteins and atherosclerosis." (PMID 39782688, 2025). "Since high-fat diets affect plasma lipids and atherosclerosis, we next asked whether hepatic Casz1 and Zfp961 are regulated in vivo by these diets." (PMID 39782688, 2025). "This study identifies hepatic Znf101/Zfp961 and Casz1 as potential therapeutic targets to alter plasma lipoproteins and reduce atherosclerosis without causing liver steatosis." (PMID 39782688, 2025). "Thus, it is likely that Casz1 and Znf101/Zfp961 are potential targets to modulate plasma lipoproteins and reduce atherosclerosis." (PMID 39782688, 2025). "To test whether KD of Casz1 and/or Zfp961 could reduce atherosclerosis, we used a mouse atherosclerosis model, in which all adult mice were transduced with mutant mouse gain-of-function Pcsk9 (mPcsk9)." (PMID 39782688, 2025). "Atherosclerosis is reduced following hepatic KD of Casz1 and Zfp961." (PMID 39782688, 2025). "Based on these studies, we speculate that Zfp961/Znf101 and Casz1 can be targeted to modulate plasma LDL and HDL and to reduce atherosclerosis." (PMID 39782688, 2025).
atrial fibrillation (1 paper, 2025). A disorder characterized by an electrocardiographic finding of a supraventricular arrhythmia characterized by the replacement of consistent P waves by rapid oscillations or fibrillatory waves that vary in size, shape and timing and are accompanied by an irregular ventricular response. "However, there are exceptions to this trend such as is observed in atrial fibrillation, where GATA4, GTF2I, and CASZ1 are both CVD proteins and DOX-correlated hub proteins." (PMID 40469117, 2025).
brain cancer (1 paper, 2023). A primary or metastatic malignant neoplasm affecting the brain. "CASZ1, which is located in 1p36.22, plays a role in the immune system, acts as a tumor suppressor gene involved in brain cancer, and truncating variants in this gene have been associated with dilatative and left ventricular non-compaction cardiomyopathy." (PMID 37012328, 2023).
diabetes (1 paper, 2023). "One patient with LP/P variants in CASZ1 and MT-TL1 presented with DCM, short stature, bilateral hearing-loss, low muscle mass, bilateral ptosis, diabetes, and multiorgan dysfunction." (PMID 37795486, 2023).
embryonal rhabdomyosarcoma (1 paper, 2023). A poorly circumscribed morphologic variant of rhabdomyosarcoma. "In subtype embryonal rhabdomyosarcoma, the aberrantly upregulated MAP kinase kinase (MEK) suppresses CASZ1 expression and impairs the autoregulated pathway composed of CASZ1, MYOD, and MYOG, thus inhibiting tumor cells from differentiating into skeletal muscles." (PMID 37509718, 2023).
epithelial ovary cancer (1 paper, 2019). "On the other hand, CASZ1 promoted the epithelial-mesenchymal transition and cancer metastasis in epithelial ovary cancer." (PMID 31481981, 2019). "In ovary epithelial cancer, on the other hand, CASZ1 expression was higher in metastatic tumors." (PMID 31481981, 2019).
hemochromatosis (1 paper, 2024). A disorder of iron metabolism characterized by a triad of HEMOSIDEROSIS; LIVER CIRRHOSIS; and DIABETES MELLITUS. "The GWAS of UK Biobank uncovered that 30 genetic loci were associated with VVs; the strongest associations found three SNPs in the CASZ1, PIEZO1, and 50 kB upstream to the HFE (hemochromatosis) genes." (PMID 39858587, 2024).
hereditary dilated cardiomyopathy (1 paper, 2025). "CASZ1 is an essential gene for cardiac development, and loss of function mutation in this gene is associated with hereditary dilated cardiomyopathy." (PMID 39844050, 2025).
hypoplastic left heart syndrome (1 paper, 2023). Hypoplastic left heart syndrome (HLHS) refers to the abnormal development of the left-sided cardiac structures, resulting in obstruction to blood flow from the left ventricular outflow tract. "A hypoplastic left heart syndrome (HLHS) patient (together with his bicuspid aortic valve mother) carried mutations affecting NLS1 regions, thus disabling CASZ1 from entering cell nuclei." (PMID 37509718, 2023). "Although CASZ1 c.73C>T is observed in ERMS and hypoplastic left heart syndrome, it is too early to say that both diseases share a common pathogenesis; considering current understanding, a common pathogenesis would be the exception and not the rule." (PMID 37509718, 2023).
idiopathic pulmonary fibrosis (1 paper, 2023). Idiopathic pulmonary fibrosis (IPF) is a nonneoplastic pulmonary disease that is characterized by the formation of scar tissue within the lungs in the absence of any known cause. "In idiopathic pulmonary fibrosis (IPF) samples, a general hypermethylation of differentially methylated regions (DMRs) of CASZ1 was observed, while immunohistochemistry demonstrated an overall downregulation in airway epithelial cells but upregulation in alveolar type II cells." (PMID 37509718, 2023).
Immunodeficiency (1 paper, 2018). Failure of the immune system to protect the body adequately from infection, due to the absence or insufficiency of some component process or substance. "Thus, Casz1 signaling pathway represents an additional pharmacologically tractable signaling axis for modulating Th17 development and targeting a variety of immunodeficiency and inflammatory disorders." (PMID 29467767, 2018).
ischemic stroke (1 paper, 2025). A stroke disorder caused by obstruction of blood flow to the brain, due to thrombotic (local blood clot formation) or embolic (due to a blood clot or other material traveling from another site) event. "Moreover, genetic variants in CASZ1 have been associated with LDL cholesterol, total cholesterol, ischemic stroke, and both systolic and diastolic blood pressure." (PMID 39844050, 2025).
kidney cancer (1 paper, 2023). Primary or metastatic malignant neoplasm involving the kidney. "Correlated with rs17035646 in our study, CASZ1 was identified to be significantly correlated with overall survival and cancer‐specific survival for kidney cancer patients." (PMID 36069056, 2023).
kidney damage (1 paper, 2023). "Variants in CASZ1 and SHROOM3 were associated with microalbuminuria and UACR, and DPEP1 along with COL4A3 were common for kidney damage and UACR." (PMID 37446387, 2023). "Variants in CASZ1 and SHROOM3 were common for microalbuminuria and UACR, and DPEP1 along with COL4A3 were common for kidney damage and UACR (p < 0.001)." (PMID 37446387, 2023).
myocardial infarction (1 paper, 2021). Gross necrosis of the myocardium, as a result of interruption of the blood supply to the area, as in coronary thrombosis. "DNA methylation in placental tissue at sites encoding PTPRN2 and CASZ1 are associated with cardiometabolic disease in adulthood, and DNA methylation in blood leukocytes at the location of the PTPRN2 gene is associated with future myocardial infarction." (PMID 34895303, 2021).
oral cancers (1 paper, 2025). "As described by Shigeishi (2023), in HPV-positive oral cancers, mutations in the PIK3CA gene are frequently observed, while there are somatic mutations in ZNF750, FGFR3, DDX3X, CASZ1, PTEN, and CYLD, differentiating them from HPV-negative oral cancers." (PMID 40284955, 2025).
renal carcinoma (1 paper, 2024). A carcinoma arising from the epithelium of the renal parenchyma or the renal pelvis. "Downregulation of CASZ1 was observed in renal cancer tissues at the protein level, which was in line with the mRNA-level findings." (PMID 39235847, 2024).
resistant hypertension (1 paper, 2022). "Recently, SNPs near CASZ1, LSP1 and RXFP2 have been associated with resistant hypertension in a genome-wide association study of 14,756 patients from Iceland, the UK Biobank and eMERGE33." (PMID 36057693, 2022). "Furthermore, it provides pathophysiological explanations for the previously observed association of CASZ1 and RXFP2 with blood pressure and resistant hypertension." (PMID 36057693, 2022).
retinal disease (1 paper, 2025). "A majority of the significantly differentially expressed (FC > 2, FDR < 1%) genes show an increase in expression with higher glucose; these include genes involved in retina development (Neurod1, Casz1, and Crxos) or those associated with retinal disease (Impg1/2, Gucy2f, Mpp4, Arl6, and Rp1)." (PMID 40568109, 2025).
retroperitoneal sarcoma (1 paper, 2019). A sarcoma involving a retroperitoneal space. "Diseases associated with CASZ1 include retroperitoneal sarcoma and retroperitoneum carcinoma." (PMID 31801612, 2019).
supravalvar aortic stenosis (1 paper, 2022). "Pathogenic variants in ELN cause supravalvar aortic stenosis but are not known to cause AVS/BAV, thus it is uncertain if it is a phenotype modifier in the family with a CASZ1 variant." (PMID 35737725, 2022).
type 2 diabetes mellitus (1 paper, 2023). A type of diabetes mellitus that is characterized by insulin resistance or desensitization and increased blood glucose levels. "Abnormal DNA methylation levels in the promoter region of the placental CASZ1 gene may lead to metabolic diseases including type 2 diabetes mellitus (T2DM)." (PMID 38053207, 2023).
vascular dementia (1 paper, 2025). A degenerative vascular disorder affecting the brain. "A novel locus for vascular dementia was discovered on chromosome 1, with castor zinc finger 1 (CASZ1) being the closest gene to the top signal." (PMID 40949174, 2025).
tumor (34 papers, 2007 to 2025). "In the NB cell line, SY5Y, an overexpression of CASZ1 not only caused morphological changes, including formation of extensions, growth cones, and dense aggregates in the cytoplasm, but also reduced tumor cell proliferation and motility in vitro." (PMID 37509718, 2023). "The loss of the CASZ1 tumor suppressor in NB tumors occurs through Chr1p LOH and/or PRC2 mediated epigenetic suppression." (PMID 36243768, 2022). "At the time of progression only, we identified the frameshift mutation of CASZ1 gene that functions as a tumor suppressor in NB contributing to cell-cycle deregulation." (PMID 35742955, 2022). "The CASZ1 expression was significantly associated with pathological type (p < 0.001), tumor grade (p < 0.001), IDH status (p = 0.037), and 1p/19q status (p < 0.001)." (PMID 36276925, 2022). "Within the CGGA cohort, CASZ1 mRNA level was positively associated with tumor proliferation index Ki‐67 (r = 0.285, p < 0.0001) and invasion index vimentin levels (r = 0.457, p < 0.0001)." (PMID 36276925, 2022). "A low expression of CASZ1 was observed in 320 cases (35.7%) and was significantly associated with large tumor size, high World Health Organization/International Society of Urological Pathology (WHO/ISUP) grade, and high T category and M category." (PMID 31481981, 2019). "Additionally, low CASZ1 expression exhibits a significant association with increasing patient age, high-risk classification of pediatric tumor group, loss of heterozygosity on chromosome 1p (1p LOH), MYCN amplification, and reduced survival probability." (PMID 38053207, 2023). "The role of CASZ1 in malignancies remains complex, which may be associated with tumor and tissue specificity." (PMID 36276925, 2022). "We performed immunohistochemical staining of CASZ1 in 896 ccRCC cases and demonstrated that a low expression of CASZ1 was associated significantly with advanced clinicopathologic parameters of ccRCC such as large tumor size, high WHO/ISUP grade, high T category and M category, and high TNM staging." (PMID 31481981, 2019). "Tumoroids demonstrated upregulation of oncogene-associated genes (Ackr3, Adcy3, Fam222) and downregulation of tumor suppressor genes (Casz1, Frk, Homer2, Pdlim1)." (PMID 40772227, 2025). "The results showed that KIRC and KIRP tumor tissues had notably higher levels of CpG-aggregated methylation of CASZ1 than did normal tissues, respectively, P less than 0.0001." (PMID 39235847, 2024). "Then we visually demonstrated the differences in methylation levels of these probes between tumor tissue and normal tissue and looked into the precise relationships that existed between these probes’ methylation levels and CASZ1 expression in ccRCC." (PMID 39235847, 2024). "We examined CASZ1 dysregulation’s possible functional involvement in RCC by examining clinicopathological characteristics such as tumor grading (ISUP grading), metastatic status, and pT and pN stages." (PMID 39235847, 2024). "Initially, we assessed the differential expression of CASZ1 in tumor and normal tissues at pan-cancer RNA level, using data from the TCGA database." (PMID 39235847, 2024). "The expression of CASZ1 in ccRCC exhibited an inverse relationship with the tumor grade (P<0.0001), metastatic status (P<0.01), and pT stage (P<0.01)." (PMID 39235847, 2024). "Three microarray datasets from the GEO database were used to verify the CASZ1 expression pattern in ccRCC tumor specimens: GSE53757 (n=72), GSE40435 (n=101), and GSE66272 (n=26)." (PMID 39235847, 2024). "The exploration of the potential of CASZ1 as a cancer biomarker for diagnosis and prognosis involves the evaluation of its prognostic value in tumor cells." (PMID 38053207, 2023). "Since CASZ1 has been shown to be tumor suppressive in several tumor types but oncogenic in others, we propose it has “double-agent” role, which is ultimately decided by cellular contexts." (PMID 37509718, 2023).
tumor (continued). "CASZ1 exhibits distinct expression patterns across various solid tumors, manifesting dual biological functions contingent on tumor type." (PMID 38053207, 2023). "In cancer, CASZ1 has emerged as a key player in tumor progression, regulating tumor growth and development." (PMID 38053207, 2023). "In contrast, several studies have described the oncogenic function of CASZ1 supporting tumor proliferation, epithelial-to-mesenchymal transition (EMT), and metastasis, suggesting a “double-agent” role among different cancer types." (PMID 37509718, 2023). "NB tumor suppressor genes, including CASZ1, CLU, NGFR, and RUNX3, are direct targets of EZH2- and H3K27me3-mediated gene silencing." (PMID 38053207, 2023). "CASZ1 plays dual roles in cancer, functioning both as a tumor suppressor and promoter, thereby influencing cancer cell metastasis." (PMID 38053207, 2023). "In NB tumor cells, the CASZ1 tumor suppressor is silenced by the NB CRC component HAND2, whereas CRC components are highly expressed." (PMID 38053207, 2023). "In NB tumor cells, the CASZ1 tumor suppressor is silenced while CRC components are highly expressed." (PMID 36243768, 2022). "As a response to decreased miR151, CASZ1 expression increases that contributes to inhibition of tumor migration in vitro and suppresses tumor genesis in vivo." (PMID 34289845, 2021). "In ERMS, mutant RAS genes are capable of suppressing CASZ1 expression and rare genetic variants of CASZ1 are found in RMS, one of which is capable of inactivating CASZ1 transcriptional and tumor suppressor activity." (PMID 32060262, 2020). "In ccRCC, based on our study, we suggest that a decreased CASZ1 expression seems to be correlated with tumor progression." (PMID 31481981, 2019). "Further functional studies are needed to validate this role of CASZ1 and to identify the mechanism of CASZ1-mediated tumor progression." (PMID 31481981, 2019). "Collectively, these data strongly demonstrated that CASZ1 elicits a tumor-suppressive role in HCC progression by inhibiting cell proliferation, migration and invasion." (PMID 29506567, 2018). "To explore the molecular mechanism by which CASZ1 exerted its tumor-suppressive function in HCC cells, we reviewed literatures and searched BioGrid 3.4 database." (PMID 29506567, 2018). "Together, these data provided strong evidence to support the tumor-suppressive function of CASZ1 in HCC growth and metastasis in vivo." (PMID 29506567, 2018). "The restoration of CASZ1 expression inhibits tumor migration in vitro and suppressed tumorigenicity in vivo." (PMID 22928040, 2012). "Several genes, such as TMPRSS4, STAR, ST7L, HAS3, FGFR3, CASZ1 and HR, were found to have gene expression changes at the very earliest stages of tumor thickening." (PMID 18442402, 2008). "The RNA expression analysis showed a decrease in PIK3CD and CASZ1 in aggressive NB, compared to more favourable NB tumours, for PIK3CD this decrease was significant also after Bonferroni correction (P=0.001)." (PMID 17940511, 2007). "We also analyzed and compared CASZ1 functions as a tumor suppressor or activator." (PMID 37509718, 2023). "However, CASZ1 can act either as a tumor repressor or an oncogene, depending on the cellular context." (PMID 37509718, 2023). "Notably, the loss of CASZ1 activity can impede embryonal rhabdomyosarcoma differentiation through RAS-MEK signaling or genetic mutations, culminating in RMS tumor development." (PMID 38053207, 2023). "Additionally, significant research has demonstrated that by limiting cell proliferation, CASZ1 can contribute to the inhibition of tumor growth in a variety of malignancies." (PMID 36344988, 2022). "CASZ1 methylation was significantly associated with the WHO grade and tumor histopathology." (PMID 36276925, 2022). "Zinc-finger TF CASZ1 is a chromosome 1p36 (chr1p36) tumor suppressor." (PMID 36243768, 2022).